ELN (elastin)
Diseases named in the same sentence as ELN in open-access papers (continued):
Sharing a sentence is not in itself a finding about the gene and the disease.
hypospadias (3 papers, 2024 to 2025). Hypospadias is the displacement of the urethral meatus on the ventrum of the penis. "In the hypospadias group, intermediate collagen fibers were the predominant type of fibers (p < 0.001), in addition to long, thin and short thin elastin fibers (p < 0.001) compared to the buried penis and the control groups." (PMID 40530185, 2025). "In the present study both elastin and collagen fibers were significantly thick in the buried penis group as compared to the control and hypospadias groups." (PMID 40530185, 2025). "Notable distinctions in collagen and elastin content are observed between normal and hypospadias-afflicted penises, affecting the stiffness and flexibility of the tunica dartos." (PMID 39476852, 2024). "Proteins such as fibulin-1, elastin, matrix metalloproteinase-1, basic fibroblast growth factor, and α-smooth muscle actin play roles in hypospadias development." (PMID 39476852, 2024). "Changes in the structure of collagen (predominantly collagen type 1), reticulin (collagen type 3), and elastin components within the dartos fascia could influence its elasticity and mobility in cases of hypospadias." (PMID 39964742, 2025). "The study concluded that the dartos fascia in buried penis and hypospadias are abnormal and contain a smaller number, however, thicker collagen and elastin fibers compared to the normal control group in addition to increased reticulin (Type III collagen) to total collagen ratio." (PMID 40530185, 2025). "The study’s aim is to investigate the differences in messenger RNA (mRNA) expression of fibulin-1, elastin, matrix metalloproteinase-1, basic fibroblast growth factor, and α-smooth muscle actin between the ventral and dorsal tunica dartos in patients with hypospadias and chordee." (PMID 39476852, 2024). "Therefore, this study aims to investigate the distinct histopathological profiles and expression of COL1A1 (collagen type 1), COL3A1 (collagen type 3), and ELN (elastin) in proximal and distal ventral dartos of patients with hypospadias compared to those with a normal penis." (PMID 39964742, 2025). "The proteins fibulin-1, elastin, matrix metalloproteinase-1 (MMP-1), basic fibroblast growth factor (bFGF or FGF-2), and α-smooth muscle actin (α-SMA) play roles in hypospadias development." (PMID 39476852, 2024). "Therefore, this protocol is designed to investigate the differences in mRNA expression of fibulin-1, elastin, MMP-1, bFGF, and α-SMA between the ventral and dorsal tunica dartos in patients with hypospadias and chordee." (PMID 39476852, 2024). "This study aims to investigate the distinct histopathological profiles and expression of COL1A1 (collagen type 1), COL3A1 (collagen type 3), and ELN (elastin) in proximal and distal ventral dartos of patients with hypospadias compared to those without hypospadias." (PMID 39964742, 2025).
infarct (3 papers, 2021 to 2025). "In our study, infarct sizes, elastin deposition, and elastin areas were significantly smaller in MCP-1-KO than CCR2-KO mice 30 days post-MI and elastin was inversely related to MCP-1 expression during the 30-day recovery." (PMID 34040032, 2021). "Notably, LTBP1 and CRIP1, along with C1QC and PRSS23 (linked to WMH and infarcts) and CEMIP and ELN (associated with WMH and microbleeds), showed strong co-localization with ThioS- positive vascular amyloid deposits, but not with parenchymal plaques." (PMID 41282800, 2025).
left ventricular hypertrophy (3 papers, 2021 to 2023). Enlargement of the LEFT VENTRICLE of the heart. "Further, they better preserved aortic endothelial function, had lower activities of matrix metalloproteinase 2 (MMP2), preserved elastin, had less fibrosis, and developed less left ventricular hypertrophy and cardiac fibrosis." (PMID 35069436, 2021).
Lipedema (3 papers, 2020 to 2025). Disorder of adipose tissue characterized by symmetric and bilateral enlargement of the lower extremities due to abnormal deposition of subcutaneous fat often in obese women. "Interestingly, individuals with Williams syndrome, a connective tissue disease where a deletion of the elastin gene has been implicated, develop a lipedema‐like phenotype in the lower extremities." (PMID 40425048, 2025). "For example, there are multiple reported genes that can confer a lipedema phenotype to tissue, and two of these genes affect tissue elasticity: ELN and TNXB (tenascin-X gene)." (PMID 33786515, 2020). "A reduction in the expression of the ELASTIN gene was found in lipedema TSAT compared to ASAT." (PMID 40425048, 2025).
liver disease (3 papers, 2016 to 2023). "ECM markers, degraded collagen III, collagen V and elastin, correlate with galactose elimination capacity and with the degree of portal hypertension." (PMID 27826254, 2016). "It prevents crosslinking between structural proteins, collagen, and elastin; At the same time, excess Cu levels may generate free radicals, inducing lipid peroxidation and affecting bone metabolism, and may lead to severe neurological issues or liver diseases." (PMID 36826855, 2023).
lymphedema (3 papers, 2006 to 2023). Excess fluid collection in tissues, causing swelling. "Elastin fibers play a crucial role in directing the flow of fluid to the lymphatic vessels in the skin, and their failure to properly support the skin and lymphatics has been linked to progressive lymphedema." (PMID 37685360, 2023). "TGF-β signalling plays a pivotal role in accelerating fibrosis by regulating profibrotic factors such as collagen, laminin, fibronectin, and elastin in secondary lymphedema." (PMID 36232660, 2022). "The development of secondary lymphedema is also accompanied by changes in the levels of metalloproteinases (enzymes capable of destroying all types of extracellular matrix proteins), which can lead to increased collagen and elastin cleavage." (PMID 37685360, 2023). "It is well-recognized that lymphedema, with chronicity, occasions the secondary proliferation of fibroblasts, keratinocytes, and adipocytes, the accumulation of collagen, and the destruction of elastin fibers within the skin." (PMID 16571129, 2006).
osteoarthritis (3 papers, 2019 to 2026). A noninflammatory degenerative joint disease occurring chiefly in older persons, characterized by degeneration of the articular cartilage, hypertrophy of bone at the margins and changes in the synovial membrane. "ELANE plays key roles in degenerative and inflammatory diseases through the proteolysis of collagen-IV and elastin, and has been implicated in osteoarthritis." (PMID 36890868, 2023). "We demonstrated that osteoarthritis, disk degeneration and scoliosis lead to distinct changes in ECM composition, particularly in the abundance of collagen and elastin." (PMID 31332239, 2019).
Peyronie disease (3 papers, 2014 to 2025). A condition characterized by hardening of the penis due to the formation of fibrous plaques on the dorsolateral aspect of the penis, usually involving the membrane (tunica albuginea) surrounding the erectile tissue (corpus cavernosum penis). "TGF-B1 has underlying role in the pathogenesis of Peyronie’s disease and elastin and collagen metabolism." (PMID 25363175, 2014). "In Peyronie’s disease patients, disruption of elastin or a decrease in elastin content has been reported and can result in penile deformities during erection and erectile dysfunction." (PMID 37001705, 2023). "Making elastin and collagen is stimulated by TGF-B1 in TADF’s that causes Peyronie’s disease phenotype formation (Hassoba, El-Sakka, & Lue, 2005)." (PMID 25363175, 2014).
preeclampsia (3 papers, 2008 to 2024). Preeclampsia is a hypertensive disorder of pregnancy that is characterized by new-onset hypertension with proteinuria presenting after 20 weeks of gestation, and depending on mild or severe forms may initially present with severe headache, visual disturbances, and hyperreflexia. "In other conditions such as preeclampsia, reduced elastin expression was observed in umbilical cord veins." (PMID 39758349, 2024).
squamous cell carcinoma (3 papers, 2014 to 2023). A carcinoma arising from squamous epithelial cells. "Analysis by cancer subtypes showed NE-degraded elastin levels were 607% higher in squamous cell carcinoma (14.6 nM), 481% higher in adenocarcinoma (12.0 nM) and 402% higher in small cell lung cancer (10.3 nM) than in healthy matched controls." (PMID 25935650, 2015). "The reason for the different results in the histological subgroups is unknown, however, lung adenocarcinomas have been shown to possess more elastin than squamous cell carcinomas." (PMID 24460801, 2014).
vitamin D deficiency (3 papers, 2021 to 2024). A nutritional condition produced by a deficiency of VITAMIN D in the diet, insufficient production of vitamin D in the skin, inadequate absorption of vitamin D from the diet, or abnormal conversion of vitamin D to its bioactive metabolites. "In angiotensin II-induced AAA mice, vitamin D deficiency was associated with increased MMP-9 activity and elastin degradation." (PMID 38923975, 2024). "Another RCT study hypothesized that vitamin D supplementation reduced elastin degradation, especially in COPD patients with vitamin D deficiency, which was evaluated by measuring plasma desmosine levels." (PMID 37375645, 2023).
age (2 papers, 2023 to 2024). A temporal measurement of the time period elapsed since an identifiable point in the life cycle of an organism. "TIMP3 upregulation preserves ECM integrity, crucial for skin resilience and regeneration, while FN1 and ELN actions further enhance wound healing and elasticity, mitigating age-related skin degradation." (PMID 39684852, 2024).
age-related macular degeneration (2 papers, 2023 to 2024). Age-related loss of vision in the central portion of the retina (macula), secondary to retinal degeneration. "We have published a review article on “elastin turnover in ocular diseases: A special focus on age-related macular degeneration”, that highlights the multitude of enzymes other than neutrophil elastase (elastase 2), cathepsin L and HTRA1 with elastase-like activity present in ocular tissues." (PMID 37174708, 2023).
allergic asthma (2 papers, 2020 to 2023). A asthma with a basis in a pathological type I hypersensitivity reaction. "Inhibition of MMP2 significantly stimulated elastin expression in airway fibroblasts from patients with allergic asthma when compared to those from normal controls." (PMID 32719611, 2020).
Anxiety (2 papers, 2020 to 2025). Intense feelings of nervousness, tension, or panic often arise in response to interpersonal stresses. "Genotype–phenotype evidence is strongest for ELN, the gene encoding elastin, which is responsible for the vascular and connective tissue features of WS, and for the transcription factor genes GTF2I and GTF2IRD1, which are known to affect intellectual ability, social functioning and anxiety." (PMID 40394675, 2025).
Ascending aortic dissection (2 papers, 2020 to 2023). A separation of the layers within the wall of the ascending aorta. "Decreased elastin concentrations within the aortic wall are strongly correlated with decreased expression of Fbln5 in patients with ascending aortic dissection, similar to our findings using Nos3−/− mice." (PMID 32801116, 2020). "TIMPs inhibit MMPs, and a previous gene expression profiling study showed decreased TIMP4 in aortic specimens of patients with type A aortic dissections, which would result in elevated MMP levels and elastin and collagen degradation in the ascending aortic wall." (PMID 37958625, 2023).
blepharoptosis (2 papers, 2022 to 2025). "The results of immunofluorescent staining showed that the CFS and LM tissues of patients with severe blepharoptosis contained strong positive expression of elastin, which was distributed in an intertwined network." (PMID 35676638, 2022). "Our previous research found that the elastin in the LM and CFS of severe ptosis in different age groups is abundant." (PMID 40240585, 2025). "Therefore, the aim of this study was to investigate the expression of elastin in the CFS and LM of patients with severe unilateral congenital blepharoptosis and to further explore the histological structure of the CFS as well as the correlation between elasticity and age." (PMID 35676638, 2022).
bronchiectasis (2 papers, 2012 to 2024). Segmental, irreversible dilation of the bronchial tree resulting in the accumulation of secretions which leads to obstruction. "Together with the previous observation in COPD11, these results strongly suggest that RA, AAA, bronchiectasis, and COPD are diseases of accelerated elastin turnover driven by an age-disease interaction where the differences between the disease groups and control becomes greater as age increases." (PMID 38413600, 2024).
bronchitis (2 papers, 2017 to 2021). An acute or chronic inflammatory process affecting the bronchi. "Subsequent elastin provocation induces apparent bronchitis-like phenotypes in the mouse lungs, including neutrophilic airway inflammation, Th17 response, and mucus hyperproduction." (PMID 33828547, 2021). "Moreover, treatment of an autophagic inhibitor 3-methyladenine (3-MA) either during CS-initiated sensitization or during elastin provocation significantly inhibited the bronchitis-like phenotypes in mice." (PMID 33828547, 2021).
bronchopulmonary dysplasia (2 papers, 2020 to 2021). Bronchopulmonary dysplasia is a chronic respiratory disease that results from complications related to lung injury during the treatment of infant acute respiratory distress syndrome in low-birth-weight premature infants or from abnormal lung development in older infants. "Conditional loss-of-function of these genes during postnatal stages leads to severe defects in alveologenesis, specifically in the generation of the elastin network, and animals display bronchopulmonary dysplasia (BPD) or BPD-like phenotype." (PMID 34901011, 2021).
cardiovascular malformation (2 papers, 2022 to 2024). "However, there were also individuals in the same family with ELN mutations who did not suffer from cardiovascular malformations or present with other types of defects." (PMID 36518217, 2022).
cavernoma (2 papers, 2023 to 2024). "Cavernous angioma or cavernoma is a sinusoidal dilatation covered by a single layer of endothelium, separated by a collagen matrix with elastin and smooth muscle, which gives it the appearance of small, agglomerated caverns when observed macroscopically." (PMID 38751883, 2024).
cerebral aneurysms (2 papers, 2023 to 2024). "In contrast, the aorta is characterized by a robust elastic network that helps maintain its structural integrity, though the loss of elastin is a critical factor in both aortic and cerebral aneurysm progression." (PMID 39595942, 2024). "During the 40–70 year period, the elastin has been degraded in a large amount, leading to decreased elasticity and resilience of arteries and possible formation cerebral aneurysms." (PMID 38129685, 2023).
cleft palate (2 papers, 2015 to 2016). Cleft palate is a fissure type embryopathy that affects the soft and hard palate to varying degrees. "The lesser amount of elastin in children and even less so in cleft palate patients might be an important factor in causing otitis media with effusion through lacking the Eustachian tube getting in its neutral position before the next contraction of the tensor veli palatini muscle." (PMID 27153847, 2016). "In our study, a significant decrease in collagen-links from the lack of LOXL3 caused cleft palate and spinal deformity, while no obvious difference was observed in the elastin cross-links in the palate and spine." (PMID 26307084, 2015). "Staining for elastin showed a significantly greater density at the hinge portion in adults compared to children, and a significantly greater density in non-cleft children compared to cleft palate children." (PMID 27153847, 2016).
colon cancer (2 papers, 2020 to 2025). "We have shown here that ELN recombinant protein increases proliferation and invasion of human colon cancer epithelial cells, indicating ELN plays an important role in regulating cancer cell adhesion, migration and invasion." (PMID 32171282, 2020). "We next assessed the level of ELN protein in human colon cancer epithelial cells compare to normal colon epithelial cells." (PMID 32171282, 2020). "In this study, we are the first to show that ELN recombinant protein further induced proliferation and migration of human colon cancer epithelial cells." (PMID 32171282, 2020). "Additionally, immunofluorescence staining demonstrated that in colon cancer, both ELN and IGF1 were primarily expressed in CAFs, with some of IGF1 also detected in cancer cells." (PMID 40659611, 2025). "ELN recombinant protein increased proliferation and wound healing in colon cancer epithelial cells." (PMID 32171282, 2020). "This study reports that CAFs isolated from colon cancer tissue, TGF-β1-induced CAFs, or HCT116 co-cultured CAFs secrete more cytokines and growth factors represented by IGF1, ELN, and SFRP2." (PMID 40659611, 2025). "The ELN recombinant protein also induces α-SMA and VIM proteins, but reduces E-cadherin in colon cancer epithelial cells." (PMID 32171282, 2020). "ELN protein was measured in human normal colon cells and colon cancer epithelial cells and tumor development was assessed in colon epithelial cells cultured in medium with or without ELN peptide on plates coated with ELN recombinant protein." (PMID 32171282, 2020). "E-cadherin (a marker of epithelial cells) was also measured in colon cancer epithelial cells incubated on plates coated with (or without) recombinant ELN and with (or without) media containing ELN peptide for 48 h." (PMID 32171282, 2020). "Transforming growth factor beta (TGF-β) was a key cytokine to induce production of ECM proteins, but it did not induce ELN expression in colon cancer cells." (PMID 32171282, 2020). "To investigate the role ELN plays in regulating tumor development in CRC, we seeded human colon cancer epithelial cells onto culture plates coated with (or without) recombinant ELN protein for 48 h." (PMID 32171282, 2020).
coronary artery stenosis (2 papers, 2023 to 2024). "The coronary stenosis induced by LCWE is characterized by severe coronary vasculitis and elastin degradation in the histological features of the coronary artery." (PMID 39063551, 2024).
cryptogenic organizing pneumonia (2 papers, 2018 to 2024). Cryptogenic organizing pneumonia (COP) is a form of idiopathic interstitial pneumonia characterized pathologically by organizing pneumonia (OP) that presents with non-specific flu-like symptoms, as well as cough and dyspnea and where no etiological agent is found. "Damaged lungs with pathologic manifestations of fibrosing organizing pneumonia displayed complete degradation or an absence of the elastin network." (PMID 38397474, 2024).
cutis laxa, autosomal dominant 1 (2 papers, 2021 to 2024). "Type 1 Autosomal Dominant Cutis Laxa is caused by a mutation in the ELN gene causing elastin dysfunction and elastogenesis hindrance." (PMID 39480826, 2024).
diabetic cardiomyopathy (2 papers, 2010 to 2012). Diabetic cardiomyopathy is a disorder of the heart muscle in people with diabetes. "AGEs-RAGE interaction contributes to diabetic cardiomyopathy by cross-linking myocardial proteins such as collagen and elastin, and by promoting collagen accumulation." (PMID 23251674, 2012).
dissection (2 papers, 2014 to 2025). The separation and isolation of tissues for surgical purposes, or for the analysis or study of their structures. "The CS side chains of the CSPG Biglycan can control elastin assembly in vascular walls, and targeted disruption of biglycan leads to abnormal collagen fibrils and aortic dissection and rupture." (PMID 24667694, 2014). "However, despite smaller AAA, Cse−/− mice displayed an increased incidence of elastin breaks and 22% of aortic dissection in Cse−/− mice, whereas no aortic dissection was observed in Cse+/+ mice." (PMID 40593101, 2025).